LZTR1 (leucine zipper like post translational regulator 1)
Diseases named in the same sentence as LZTR1 in open-access papers (continued):
Sharing a sentence is not in itself a finding about the gene and the disease.
tumor (continued). "Data about Xenopus tropicalis and Rattus norvegicus with Lztr1 and Lztr1 variants, respectively, showed the following phenotypes: cardiovascular, central nervous, and gastrointestinal system disease; thyroid disease; benign neoplasm; cancer and pre-malignant neoplasm." (PMID 40724954, 2025). "Variants in LZTR1 can disrupt the RAS/MAPK signaling pathways and lead to uncontrolled cell proliferation and tumor development." (PMID 40941673, 2025). "Tumor-suppressor genes, including APC, BARD1, HMMR (RHAMM), KLLN, LZTR1, MCPH1 (BRIT1), MLH1, NF1, RB1CC1 (FIP200), SLC22A18, and SPTBN1, have been found to increase the risk of disease and tumor development." (PMID 40941673, 2025). "LZTR1 encoding leucine-zipper-like transcription regulator 1, which belongs to the BTB-POZ protein superfamily, is a tumour suppressor gene." (PMID 39415983, 2024). "The study about leucine zipper-like transcriptional regulator 1 (LZTR1) presented that LZTR1 deficiency, both in vitro and in vivo, induces EMT and ECM deposition, which contributes to tumor progression and metastasis." (PMID 39201656, 2024). "Identification of novel proteins interacting with LZTR1 will help in understanding the molecular function of LZTR1 in tumor metastasis." (PMID 37626065, 2023). "Leucine-zipper-like transcription regulator 1 (LZTR1) is able to inhibit tumor cell proliferation by degrading Ras proteins." (PMID 38174069, 2023). "Here, we showed that LZTR1 deficiency induces EMT and promotes tumor growth and metastasis in xenograft tumor models." (PMID 37626065, 2023). "Within 22q11.21, we identify LZTR1—a known tumor suppressor in other cancers—as a key candidate driver of metastasis." (PMID 35197475, 2022). "Here, the authors integrate genomic and clinical data from 104 patients and identify late-arising focal amplifications of chr22q11.21 and LZTR1 as a key tumour promoter in this region." (PMID 35197475, 2022). "Unexpectedly, LZTR1 – a known tumor suppressor in other cancers – is a key candidate oncogene in this cytoband." (PMID 35197475, 2022). "Unique aspects of our study include the broad range of tumor specimens analyzed and the utilization of cells harboring different oncogenes that modulate LZTR1 activity." (PMID 35197475, 2022). "Our genomic and functional experiments provide critical insights into the pathogenesis of this disease and strongly implicate LZTR1 as a tumor promoter and promising therapeutic target." (PMID 35197475, 2022). "Based on these findings, we performed a comprehensive analysis of LZTR1 signaling pathways and obtained functional evidence for LZTR1 as a tumor promoter." (PMID 35197475, 2022). "Recurrent tumors were similar to the primary tumors with the exception that the second and third recurrence from tumor #8, as well as recurrence from tumor #3 had an additional amplification of the LZTR1 gene." (PMID 34495383, 2021). "LZTR1 was suggested to possess tumor-suppressing function in cancers and be related to cell apoptosis." (PMID 33028809, 2020). "Accordingly, LZTR1 has a tumor suppressor phenotype following CRISPR-mediated knockout in KRAS-dependent, but not RAS-independent, MM lines, and LZTR1 knockdown amplified KRAS protein expression in KRAS-dependent MM lines via decreased K48-linked ubiquitination of KRAS." (PMID 41542462, 2026). "SWN-related hybrid tumours are characterized by a typical mosaic staining pattern of protein SMARCB1 (positive and negative nuclei) and a remarkable loss of LZTR1 (only few positive nuclei left) in LZTR1-SWN." (PMID 41247561, 2025). "The SMARCB1 and LZTR1 genes are involved in the regulation of cell growth and tumor suppression." (PMID 40764996, 2025). "Based on our results and those of previous studies indicating that LZTR1 acts as a tumor suppressor in vitro, we examined whether it also serves as a tumor suppressor in a xenograft tumor model." (PMID 37626065, 2023).
tumor (continued). "However, the role of LZTR1 in tumor metastasis and the target molecules of LZTR1, excluding the RAS subfamily, are not clearly understood." (PMID 37626065, 2023). "Conversely, patients with low levels of LZTR1 preferentially harbor a hot tumor microenvironment, which might provide benefit from immunotherapy." (PMID 35197475, 2022). "One of these suspected tumour suppressor genes is likely to be LZTR1." (PMID 27921248, 2017). "However, comprehensive mutation testing of LZTR1, SMARCB1, and NF2 using DNA derived from blood and different tumour samples of the patient is the method of choice to distinguish between the two conditions." (PMID 27921248, 2017). "Additionally, the c.353G>A likely pathogenic variant (VAF 5% and 38%) in the LZTR1 gene impairs RAS ubiquitination, leading to the deregulation of the RAS/MAPK pathway, which promotes proliferative signaling and contributes to subclonal tumor progression." (PMID 40076915, 2025). "Therefore, it was reasonable to suggest that LZTR1 exerted tumor-suppressive effect through suppressing MAPK pathway, and that LZTR1 might mediate the regulation of LL22NC03-N14H11.1 on H-RAS (G12V) in HCC." (PMID 33028809, 2020). "These tumor suppressor genes found on chromosome 22, near the NF2 region, include SMARCB1 and LZTR1." (PMID 40337438, 2025). "In conclusion, it was suggested that LL22NC03-N14H11.1 facilitated tumor growth and metastasis of HCC through LZTR1 in vivo." (PMID 33028809, 2020). "Multi-omics analysis to clarify the pathways related to tumor progression showed that MAPK signaling, epithelial-mesenchymal transition (EMT), and extracellular matrix (ECM) remodeling-related gene ontology terms were enriched in LZTR1 knockout cells." (PMID 37626065, 2023). "Although the expression of LZTR1 did not significantly change between tumor samples and normal samples, elevated IR still implies a decreased level of spliced and functional products." (PMID 38067392, 2023). "The potential oncogenic role these E3 ligases play in the absence of LZTR1 has not yet been identified and the E3 ligases may warrant further investigation as potential therapeutic targets in this subset of tumours." (PMID 33432111, 2021). "Thus, it appears that heterozygous loss of multiple genes residing in chromosome 22, including tumor suppressors, such as CHEK2, LZTR1 and SMARCB1, confers no proliferative advantage to the cells." (PMID 32724039, 2020). "In these tumours, neither SMARCB1 nor LZTR1 mutations were detected." (PMID 27921248, 2017). "Lastly, LZTR1, characterized as a negative regulator of RAS39, no longer acted as a tumor suppressor under low glutamine conditions, and correspondingly oncogenic NRAS became less essential." (PMID 36115844, 2022).
cancer (33 papers, 2014 to 2025). A tumor composed of atypical neoplastic, often pleomorphic cells that invade other tissues. "This part of the study focused on finding a correlation between familial occurrence of cancer and detected genetic variants of LZTR1." (PMID 40724954, 2025). "Mutations and deletions targeting LZTR1 have been reported in multiple cancers including colorectal carcinoma." (PMID 38654044, 2024). "To comprehensively identify the cellular signaling and physiological functions associated with LZTR1 deficiency in cancers, we performed multi-omics analyses using A549-WT and A549-KO cells." (PMID 37626065, 2023). "The association of the locus spanning the LZTR1 gene is also notable as this gene encodes an important leucine-zipper transcriptional regulator that is linked to cell proliferation in cancer." (PMID 35328087, 2022). "For this reason, the analysis of studies with model organisms could clarify LZTR1 variant function in cancer development." (PMID 40724954, 2025). "RIT1 is the most upregulated RAS subfamily member in LZTR1 deficiency in several cancer types." (PMID 37626065, 2023). "Mutations in LZTR1 have been identified in patients with several types of cancer." (PMID 37626065, 2023). "Recurrent P/LP variants were identified in individuals diagnosed with cancer from distinct families, in the following cancer genes: BRCA1 (n = 3), LZTR1 (n = 3), HNF1A (n = 2), CHEK2 (n = 2), MITF (n = 2), and CHD4 (n = 2)." (PMID 37377903, 2023). "Elucidating the implications of LZTR1-mediated regulation of KRAS protein levels in cancer may offer insights into therapeutic strategies targeting KRAS-driven malignancies." (PMID 38453365, 2024). "KLHL9, LCMT2, and LZTR1 have been reported to influence cancer progression in different contexts." (PMID 35656299, 2022). "However, despite these findings, LZTR1 is amplified in a subset of carcinomas (up to 8.3%), including bladder, uterine, and lung cancers." (PMID 35197475, 2022). "Some of them were cancer-type specific (such as CSF3R), while some others (such as LZTR1 and ERCC4) showed consistent alterations across multiple cancers." (PMID 38067392, 2023). "Consistently, LZTR1 has been found by mass spectroscopy tointeractwith a Ras-related small GTPase, RIT1, an oncoprotein highly involvedin Noonan syndrome and cancer." (PMID 33792302, 2021). "We identified genes for which ASEs were observed in both the Afro-Caribbean cohort and the Jurkat cells expressing Tax or HBZ, including cancer genes EIF4A2, IKBKB, LZTR1, STAT6 (for Tax); CARS, MDM2, IKZF1 (for HBZ); and EWSR1, MUTYH, and PTPRC (for both Tax and HBZ)." (PMID 34543356, 2021).
genetic disorder (3 papers, 2020 to 2023). "Our findings provide novel insights into the treatment of LZTR1-related tumors and other genetic disorders." (PMID 37626065, 2023).
nervous system disorder (3 papers, 2020 to 2024). A non-neoplastic or neoplastic disorder that affects the brain, spinal cord, or peripheral nerves. "We used rhGH in the proband with caution due to risks of nervous system disorders associated with LZTR1 variants." (PMID 39415983, 2024). "LZTR1 interacts with CUL3 and neurofibromin 1 (NF1) to regulate nighttime sleep by increasing GABA receptor signaling and has been associated with RAS-related neurological diseases caused by NF1 deficiency." (PMID 39062695, 2024).
adenocarcinoma (1 paper, 2026). A common cancer characterized by the presence of malignant glandular cells. "Together, these data suggest that RAS stability is differentially regulated in hematologic cancers versus adenocarcinomas and further support the notion that PPP1R2/PP1C/LZTR1-dependent regulation of KRAS stability is a feature of hematologic cancers." (PMID 41542462, 2026).
hematologic cancer (1 paper, 2026). "Given the increased role of LZTR1 as a RAS-regulator in hematologic cancers, this dual function may explain why A146 mutations are enriched in hematologic malignancies but are largely absent from pancreatic and many other epithelial cancers." (PMID 41542462, 2026). "The preferential regulation of RAS by PP1C and LZTR1 in hematologic cancers may be caused by multiple factors." (PMID 41542462, 2026). "These screens and follow-up experiments reveal unique biology governing oncogenic RAS signaling specific to MM and other hematologic cancers, centered on the phosphorylation-dependent, LZTR1-mediated degradation of mutant RAS isoforms." (PMID 41542462, 2026).
LZTR1 also shares sentences with these, for which no sentence is quoted: influenza (13 papers); virus infection (10); diabetes (4); hepatocellular carcinoma (4); Neurofibromatosis Type 2 (4); childhood cancer (2); co-infection (2); Ewing sarcoma (2); Hepatitis (2); Legius syndrome (2); neurofibromatosis type (2); schizophrenia (2); type 2 diabetes (2); acute lymphoblastic leukemia (1); adenoma (1); Alzheimer disease (1); asthma (1); astrocytic neoplasms (1); astrocytoma (1); Barth syndrome (1); benign neoplasm (1); benign nervous-system tumors (1); brain cancer (1); café-au-lait macules (1); cardiofaciocutaneous syndrome (1); cardiospondylocarpofacial syndrome (1); Carvajal syndrome (1); cataract (1); chronic hepatitis C (1); Chylothorax (1).
A further 50 diseases each share a sentence with LZTR1 in 1 paper.